RNU6-312P (RNA, U6 small nuclear 312, pseudogene)
Gene: Small nuclear RNA gene on chromosome 2 (200,881,715 to 200,881,821, reverse strand). Ensembl gene ENSG00000201499.
Homologues: Orthologues: chimpanzee U6 (100% identical), macaque U6 (93% identical), rabbit U6 (87% identical), dog U6 (84% identical), guinea pig U6 (84% identical), rabbit U6 (83% identical), dog U6 (82% identical), pig U6 (80% identical). Paralogues in human: RNU6-11P (88% identical), RNU6-37P (88% identical), RNU6-812P (88% identical), RNU6-1131P (87% identical), RNU6-15P (87% identical), RNU6-16P (87% identical), RNU6-21P (87% identical), RNU6-552P (87% identical), RNU6-556P (87% identical), RNU6-61P (87% identical), RNU6-936P (87% identical), RNU6-1 (86% identical), and 1289 more.